TLR3 (toll like receptor 3)
Diseases named in the same sentence as TLR3 in open-access papers (continued):
Sharing a sentence is not in itself a finding about the gene and the disease.
Hepatitis (17 papers, 2011 to 2026). Inflammation of the liver. "Several investigations have examined the association of TLR3 polymorphisms with hepatitis virus acquisition and hepatitis virus-related diseases." (PMID 27227908, 2016). "Thus, the TLR3/4-TBK1-IRF3-IL-33 signaling pathway activation by HBV plus carcinogen is a mechanism that explains hepatitis and HCC risk associated with HBV infection, which can be blocked by statin to suppress hepatitis and HCC." (PMID 40579434, 2025). "Here TNF-α, which emerged from a response to a viral pathogen associated molecular pattern (PAMP) recognized by the TLR3, was most probably produced by Kupffer cells as their previous chemical depletion prevented the development of hepatitis in poly I:C challenged Ripk1LPC-KO mice." (PMID 30622241, 2019). "In this study, we investigated the role of LIGHT in TLR3 involved liver pathogenesis by using a mouse model of TLR3 agonist poly(I:C)-induced hepatitis." (PMID 36654880, 2023). "Taken together, these findings demonstrate that LIGHT plays an important role in the initiation and development of TLR3-triggered hepatitis." (PMID 36654880, 2023). "It has been reported that activation of hepatic NK cells and Kupffer cells triggered by TLR3 initiates the liver injury in poly(I:C)-induced hepatitis model." (PMID 36654880, 2023). "Upon recognition of hepatitis C virus (HCV) infection by Toll-like receptor 3 (TLR3) and retinoic-acid inducible gene I (RIG-I), the innate immune response is promptly activated in hepatocytes." (PMID 24490062, 2013). "The bystander hepatitis induced by TLR3 and TLR9 stimulation produced a steady increase in the expression of VCAM-1." (PMID 23110209, 2012). "TUNEL-positive cells were found more frequently in mice that received TLR3 and 9 ligands alone or in association with NP-CTL transfer, confirming the bystander hepatitis caused by TLR stimulation (p<0.0001)." (PMID 23110209, 2012). "In summary, in this model, transferred autoreactive T cells are preferentially recruited by the liver, in response to homing and recruitment signals up-regulated by TLR3 and 9 stimulation and the ensuing bystander hepatitis." (PMID 23110209, 2012). "Expression of LIGHT depends on NF-κB activation in TLR3-mediated hepatitis." (PMID 36654880, 2023). "The results suggest that breaking LIGHT signaling events may have therapeutic benefit in treating TLR3-mediated hepatitis." (PMID 36654880, 2023). "Thus, TLR3 and 9 stimulation can lead to bystander hepatitis." (PMID 23110209, 2012). "Liver inflammation, assessed by ALT levels, correlated with platelet- and leukocyte-LGP2, in addition to leukocyte-TLR3, -TLR6, -TLR7, and -RIG-I." (PMID 40825056, 2025). "However, it is not known if a TLR3 and 9-induced pro-inflammatory environment in presence of circulating autoreactive T cells (similar to a viral bystander hepatitis in a predisposed individual) is sufficient to break tolerance and lead to a chronic autoimmune liver disease." (PMID 23110209, 2012). "rhamnosus CRL1505 exerts immunomodulatory and hepatoprotective effects during TLR3-driven hepatitis and that mbf-mediated adhesion is not required for this protection." (PMID 41897754, 2026). "Therefore, stimulation of TLR3 and 9 promotes homing of CXCR3+ and CXCR6+ T cells, including autoreactive T cells, resulting in bystander hepatitis." (PMID 23110209, 2012).
pneumonia (17 papers, 2012 to 2025). An acute, acute and chronic, or chronic inflammation focally or diffusely affecting the lung parenchyma, caused by an infection in one or both of the lungs (by bacteria, viruses, fungi, or mycoplasma.). "There is a close relationship between the presence of TLR3 rs5743313/CT and an increased risk of pneumonia in children infected by the pandemic A/H1N1/2009 influenza virus." (PMID 23151015, 2012). "We found a close relationship between the presence of the TLR3 rs5743313/CT polymorphism and an increased risk of pneumonia in children infected by the pandemic A/H1N1/2009 influenza virus." (PMID 23151015, 2012). "Similarly, TLR3 polymorphisms have been associated to pneumonia development in children with influenza virus infection." (PMID 25071766, 2014). "Also, Tlr3-deficient mice showed better survival in a murine model of influenza A virus-induced acute pneumonia, despite the impaired immune response and virus clearance." (PMID 22570612, 2012). "The deficiencies of autosomal Toll-like receptor 3 (TLR3) and TLR7 linked to the X chromosome are inborn errors of type I interferons that are found in around 1% to 5% of younger patients (under 60 years old) with critical pneumonia, while a lower proportion of older patients have them." (PMID 37460909, 2023). "It has been reported that lasting activation of TLR3 is detrimental to IAV-induced acute pneumonia, conversely, IAV-infected TLR3−/− mice have an unexpected survival advantage with significantly lower viral titer, less inflammatory mediators, and fewer pathological changes in lung." (PMID 29570670, 2018).
Autoimmunity (16 papers, 2011 to 2025). The occurrence of an immune reaction against the organism's own cells or tissues. "Intracellular TLRs recognise bacterial and viral nucleic acids and self-nucleic acids in autoimmunity; these include TLR3, TLR7, TLR8, TLR11, and TLR12." (PMID 37761018, 2023). "This opens possible novel therapeutic avenues for autoimmunity involving endocytosis-dependent TLR3/4/7 activation." (PMID 36498932, 2022). "In principle, endogenous nucleic acids can trigger TLR3-dependent immune responses, thereby contributing to inflammatory pathologies and autoimmunity." (PMID 36498932, 2022). "Here we show that the TLR3 induced production of T cell guiding chemokines by human LNSCs is diminished at a very early stage of systemic autoimmunity." (PMID 29379035, 2018). "Moreover, TLR3 induces thymic overexpression of the alpha subunit, AChR, and promotes an anti-AChR autoimmune response, which supports the hypothesis of an EBV contribution to B-cell-mediated autoimmunity through TLR3 in MG thymomas." (PMID 35894054, 2022). "TLR3 appears to exist as a functional receptor on the cell membrane more frequently than other endosomal TLRs, probably because endogenous agonists of TLR7, TLR8, and TLR9 are more abundant than dsRNA in uninfected cells, and therefore surface localization of TLR3 poses a lower risk of autoimmunity." (PMID 33597952, 2020). "Therefore, it would be important to investigate the effects of different levels of type I IFNs that are activated via TLR3 in resistant and susceptible mice to determine its impact on the development of TMEV-induced demyelinating disease, which bears both viral and autoimmunity components." (PMID 22189096, 2011). "In the host body, particular caution is required in activating nucleic-acid-sensing TLRs, such as TLR3, TLR7, and TLR9, to avoid self-recognition and thus the induction of autoimmunity." (PMID 31892731, 2019). "By maturing WT or IL-12 deficient BMDCs with Poly I∶C or LPS and pulsing mature DCs with GP peptides, the impact of TLR3 or TLR4 stimuli on the requirement for IL-12 in breaking tolerance and inducing autoimmunity can be evaluated." (PMID 21931625, 2011). "We demonstrated that the transfer of TLR3 or TLR4 matured DCs presenting self-antigens promotes CD8 T cell mediated autoimmune responses and overt organ specific autoimmunity in vivo." (PMID 21931625, 2011). "We have established a murine model to examine whether TLR3 or TLR4 mediated DC maturation has an impact on the cytokines required to break tolerance and induce T-cell-mediated autoimmunity." (PMID 21931625, 2011). "Although the endosomal localization isolate TLR3, 7, 8 and 9 away from self-nucleic acids in the extracellular space, still self-RNA or -DNA can become a potent trigger of cell activation when transported into TLR-containing endosomes and can lead to sterile inflammation and autoimmunity." (PMID 34108972, 2021). "However, UNC93B1 upregulation may also increase the responsiveness of TLR3, TLR7, TLR8, and TLR9 to their agonists, and conditions that lead to increased UNC93B1 expression may yield autoimmune disorders." (PMID 33597952, 2020). "Similarly, synthetic circRNAs engineered to mimic viral structures may unintentionally trigger innate immune activation through pattern recognition receptors (PRRs) such as RIG-I, MDA5, or TLR3, potentially leading to systemic inflammation or autoimmunity if not carefully controlled." (PMID 41438756, 2025). "CB4-infected TLR3+/- mice have skewed IFN-I responses that favor increases in IFN-α and increases in effector T cells at the site of autoimmunity that ultimately do not protect from T1D." (PMID 34804036, 2021). "Although TLR3 signaling is critical for survival against CB4 in NOD mice, we observed that IFN-I and adaptive responses produced as a result from TLR3 signaling to clear the virus are not similarly compatible with protection from autoimmunity." (PMID 34804036, 2021).
dengue (16 papers, 2010 to 2025). "In the context of dengue virus infection, research has suggested that the presence of the polymorphic TT genotype for TLR3 rs3775291 C/T was observed with greater frequency in the infected cohort compared to the control group." (PMID 40831704, 2025). "Dengue patients with low levels of leukocytes and lymphocytes, and high levels of monocytes and IgG, were more likely to be TLR3-rs3775291-C/C." (PMID 33138336, 2020). "Dengue patients with low levels of leukocytes and lymphocytes, and high levels of monocytes, IgM, and IgG, were more likely to be TLR3-rs6552950-A/A." (PMID 33138336, 2020). "TRAIL+ NK cell frequency and TRAIL MFI on NK cells were significantly higher in PBMC during acute dengue fever as compared to those in healthy donors, as well as CD107a expression and TLR3-positive NK cells." (PMID 29038620, 2017). "A link between TLRs expression and the severity of dengue was observed: patients with dengue fever express higher levels of TLR3 and TLR9 than patients with DHF." (PMID 23469297, 2013). "The MFI results showed that expression of TLR3 in mDCs was significantly higher in dengue patients than in HCs, on days 3 and 5 of illness (p<0.05 and p<0.01, respectively)." (PMID 23469297, 2013). "This study demonstrates a synergistic role for RIG-I, MDA5 and TLR3 in restricting dengue virus infection." (PMID 21245912, 2011). "TLR3 was also shown to have a role in the regulation of the inflammatory response in dengue infected umbilical vein endothelial cells." (PMID 21810247, 2011). "Indeed, TLR3 and the inflammasome NLRP3 activation were associated with the pathogenesis of dengue, especially in the development of hemorrhages." (PMID 35632732, 2022). "In mDCs of dengue patients, TLR3, TLR4 and TLR9 reached maximum expression on day 5 of illness." (PMID 23469297, 2013). "Previously, Tsai and co-workers reported that TLR3 induces an anti-dengue response in HEK293 cells." (PMID 23469297, 2013). "Lastly, corroborating the relationship of TLR3 with mild outcomes, the increased expression of TLR3 in DCs of patients with dengue fever (DF) was described." (PMID 35632732, 2022). "In summary, Toll-like receptors such as TLR3, TLR7, and TLR8 play significant roles in the innate immune response against dengue virus infection." (PMID 37631896, 2023). "Increased TLR3 and TLR9 expression was found in DCs of patients with dengue fever (DF) early in infection, and poor stimulation of TLR3 and TLR9 was observed in DCs from patients with severe manifestations, suggesting a role for TLRs in dengue pathogenesis." (PMID 34603272, 2021). "We report here that CD16+ NK cell subpopulations are more likely to be activated in mild cases of dengue, when TRAIL, CD107a, and TLR3 were analyzed." (PMID 29038620, 2017). "Previous reports showed that TLR3, MDA5 and RIG-I are involved in intracellular detection of dengue virus infection." (PMID 27449021, 2016). "TLR3-mediated innate and inflammatory responses were demonstrated to be protective against HIV, CMV and Dengue virus infections, while TLR3 stimulation results in detrimental disease outcomes in Influenza A virus and Punta Toro virus infections." (PMID 25452586, 2015). "The mRNA for several innate receptors was increased following dengue virus plus dengue-immune sera treatment, including PKR, RIG-I, MDA5, TLR3 and TLR7." (PMID 22479521, 2012). "TLR-3 and TLR-7 have been reported to play important roles in inhibiting dengue virus infection in U937 and HEK293 cells, respectively." (PMID 21200427, 2010). "Neither are individually critical in reovirus and in dengue virus infection but the presence of either in combination with Toll-like receptor 3 (TLR3) is critical to have effective anti-viral repsonses." (PMID 31379819, 2019). "Like CD107a expression, TLR3 expression was not different among dengue severity, but segregated healthy donors and mild patients." (PMID 29038620, 2017).
dengue (continued). "Therefore, we evaluated the expression levels of TLR2, TLR3, TLR4 and TLR9 in mDCs, pDCs and monocytes of dengue patients, and compared them to the HCs." (PMID 23469297, 2013). "Since dengue is a single stranded RNA virus, TLR3 may not respond as it is known to recognize viral double stranded RNA." (PMID 24727912, 2014). "Increased expression of TLR3 and TLR9 in DCs of patients with dengue fever (DF) early in infection was detected." (PMID 23469297, 2013).
Obesity (16 papers, 2013 to 2025). Accumulation of substantial excess body fat. "Evidence associates the increased expression of TLRs, except TLR3, with inflammation and decreased insulin sensitivity in obesity-induced AT." (PMID 40076851, 2025). "In loss-of-function animal models, although TLR3-deficient mice fed with a HFD developed obesity, they exhibited improved glucose tolerance and reduced liver steatosis compared with wild-type (WT) obese mice." (PMID 31582899, 2019). "Conversely, another study indicated that TLR3-deficient mice with HFD-induced obesity exhibit increased glucose tolerance and serum insulin and decreased serum levels of very low-density lipoproteins and triglycerides (TG)." (PMID 31582899, 2019). "First, mice deficient in the two TLRs that use TRIF—TLR4 and TLR3 —are protected from obesity-induced VAT inflammation and insulin resistance." (PMID 26317499, 2015). "In a following set of experiments, we assessed whether TLR-3 deficiency affected the development of obesity-induced adipose tissue inflammation." (PMID 25867514, 2015). "TLR3 appears to regulate the AT homeostasis of the inflammatory state, but this regulatory property is altered in obesity." (PMID 40076851, 2025). "This decrease in TLR3 expression and decreased leptin receptors are also shown in human AT in a setting of obesity-related inflammation." (PMID 40076851, 2025). "Taken together, TLR3 remains the independent predictor of adipose SRA1 expression in settings of both obesity and T2D." (PMID 36552771, 2022). "In individuals with obesity (N = 64), TLR3, TLR7 and IRAK1 were detected as the independent predictors of adipose SRA1 expression." (PMID 36552771, 2022). "AT-SRA1 expression was independently predicted by TLR3/TLR7 and IRAK1 in those with obesity and by TLR3/TLR9 in individuals with T2D." (PMID 36552771, 2022). "This concept is supported by evidence that several inflammatory RBPs, including TLR3, TLR7, and PKR, are involved in the induction of obesity-associated chronic inflammation." (PMID 31482095, 2019). "TLR3 appears to play a redundant role in obesity-induced inflammation and insulin resistance, which should be investigated." (PMID 31582899, 2019). "Next, we correlated the gene expression levels of TLR-3 in subcutaneous adipose tissue samples from 80 healthy donors, with markers of obesity, inflammation and insulin sensitivity." (PMID 25867514, 2015). "Here, we identified profound expression of TLR-3 in adipocytes and investigated its role during diet-induced obesity." (PMID 25867514, 2015). "Possibly, TLR-3 exerts differential effects in the liver versus adipose tissue during the development of HFD-induced obesity." (PMID 25867514, 2015). "TLR-3 is also a molecule that is active in the mechanisms of obesity-induced inflammation." (PMID 40076851, 2025). "Our data further show that TLR3/TLR9 expression was associated independently with the expression of SRA1 in individuals with T2D, while TLR3, TLR7 and IRAK1 were identified as the independent predictors of adipose SRA1 expression in individuals with obesity." (PMID 36552771, 2022). "Recently, one study showed that TLR3 ablation prevented obesity and metabolic disorders." (PMID 35009003, 2022). "Concurrent findings in PKR and TLR3 support the possibility that endogenous RNA species become “pathological” and are recognized by the dsRNA sensors, leading to the deterioration of systemic glucose and energy metabolism in obesity." (PMID 31482095, 2019). "In the current study we examined whether TLR-3-signalling is involved in the development of adipose tissue inflammation and insulin resistance during the development of obesity." (PMID 25867514, 2015). "In vivo, TLR-3 deficiency did not significantly influence HFD-induced obesity, insulin sensitivity or inflammation." (PMID 25867514, 2015). "However, TLR-3 appears to play a redundant role in obesity-induced inflammation and insulin resistance." (PMID 25867514, 2015).